UBE3A (ubiquitin protein ligase E3A)
Diseases named in the same sentence as UBE3A in open-access papers (continued):
Sharing a sentence is not in itself a finding about the gene and the disease.
Angelman syndrome (continued). "Since ubiquitination controls the diverse endpoints of proteins, in Angelman syndrome patients, UBE3A substrates are likely to be negatively affected by the lack of functional UBE3A in neurons." (PMID 31130875, 2019). "Lack of UBE3A leads to Angelman syndrome (AS), while its increase is among the most prevalent genetic causes of autism (e.g., Dup15q syndrome)." (PMID 31798818, 2019). "This is contrast to imprinted Ube3a, where pups lacking this maternally expressed gene have increased USVs, paralleling findings in individuals with Angelman syndrome where UBE3A is the key candidate." (PMID 29186532, 2018). "Patients with Angelman syndrome do not express UBE3A in neural tissue and show elevated EEG delta power, the opposite electrophysiological phenotype as Dup15q syndrome." (PMID 27977700, 2016). "Despite this robust age-related decrease in UBE3A expression, older individuals do not develop Angelman syndrome." (PMID 26441497, 2015). "Angelman syndrome, a severe neurodevelopmental disease, occurs primarily due to genetic defects, which cause lack of expression or mutations in the wild-type E6AP/UBE3A protein." (PMID 25633294, 2015). "Pharmacological methods of expressing paternal UBE3A, while successful at initiating protein expression, have not been characterized to ameliorate Angelman syndrome phenotypes in vivo." (PMID 26441497, 2015). "A simple model for Angelman syndrome is that lack of UBE3A increases the concentration or persistence of its target proteins." (PMID 24946931, 2014). "Nevertheless, the CDKL5 variant was still suspicious due to the clinical phenotype of the patient, since the referring physician considered his disease to be consistent with Angelman syndrome, and previously ruled out UBE3A methylation and sequence defects." (PMID 24215330, 2013). "Also, the Snrpn-Ube3a locus is involved in the classic sister imprinting disorders Prader-Willi syndrome (OMIM: 176270) and Angelman syndrome (OMIM: 105830), both of which display developmental delay and deficits in cognitive function." (PMID 23580197, 2013). "The patient was originally referred to our laboratory because of suspected Angelman syndrome, which was ruled out as SNRPN methylation analysis showed a biparental pattern and no UBE3A gene mutation was found." (PMID 22475481, 2012). "The identification of UBE3A as an ASPM interactor is not surprising as more than 80% of Angelman syndrome patients have microcephaly." (PMID 21633703, 2011). "We assessed the effects of CBD in Angelman syndrome model mice lacking the Ube3a gene and found that chronic injection of CBD increased rapid-eye movement sleep during the dark cycle, restored "Siesta", improved sleep homeostasis, and reduced spontaneous seizures following flurothyl kindling." (PMID 42265437, 2026). "Thus, it is deemed that the absence of UBE3A results in the characteristic features of Angelman syndrome." (PMID 30899624, 2019). "More precisely, inhibition of the DUB counteracting the action of the E3 ligase UBE3A may help restoring the non-pathological ubiquitination levels of UBE3A substrates in Angelman syndrome patients." (PMID 31130875, 2019). "Therefore, if a patient inherits two copies of the paternal allele, as in cases of UPD, they will not possess an active form of UBE3A within the brain and thus will present with Angelman syndrome." (PMID 30899624, 2019). "The best known example of these defects is Angelman syndrome characterised by intellectual disability, absence of speech, motor dysfunction and seizures (MIM 105830) caused by loss of function of the imprinted gene UBE3A (ubiquitin protein ligase E3A)." (PMID 25306138, 2014). "Similarly, in the tammar wallaby, UBE3A and SNRPN (the only two genes of the orthologous Prader Willi Syndrome - Angelman Syndrome domain that could be identified) are located on different chromosomes and are not imprinted." (PMID 22899817, 2012).
Angelman syndrome (continued). "In short, decreasing or increasing Ube3a levels alone may contribute in different ways in both Angelman syndrome and 15q duplication autism phenotypes rather than resulting in clear diametrically opposed affects." (PMID 22916201, 2012). "However, our results build on findings in Angelman syndrome showing that children with 15q11-q13 deletions (deletion Angelman) have lower beta (23 Hz) power than children with other etiologies that principally affect UBE3A (nondeletion Angelman)." (PMID 32791992, 2020).
autism (102 papers, 2010 to 2025). Persistent deficits in social interaction and communication and interaction as well as a markedly restricted repertoire of activity and interest as well as repetitive patterns of behavior. "It has been well studied that the gain of function and overdosage, especially duplication, of maternal UBE3A, causes penetrance of the autism spectrum (Dup15q specifically)." (PMID 40076922, 2025). "It was observed that UBE3A staining is lower in the oligodendroglia from a mouse model with a gain of function mutation linked to autism." (PMID 40076922, 2025). "In contrast, duplication or triplication of maternal chromosome 15q11-13, the chromosomal region where UBE3A resides, causes a prevalent genetic form of autism known as Dup15q syndrome." (PMID 40316779, 2025). "Ubiquitin protein ligase E3A (UBE3A) is one of the most extensively studied autism-linked candidate genes." (PMID 39202440, 2024). "ASD diagnosis due to genetic alterations in UBE3A accounts for 1-2% of all autism cases, making it one of the strongest genetic risk factors for autism." (PMID 38316900, 2024). "Overdosage of autism risk gene Ube3a produces sex-dependent alterations in gene expression and brain connectivity." (PMID 38996019, 2024). "This syndrome is due to the loss of function of the UBE3A gene and is associated with intellectual disability, epilepsy, ataxia, and autism." (PMID 37190119, 2023). "The UBE3A gene’s gain-of-function mutation, triplication, and duplication are associated with autism, a condition clinically described by seizures, speech anomalies, and intellectual disability." (PMID 38248358, 2023). "A genome sequencing study by Iossifov and colleagues found that autism can be associated with a missense mutation [T485A] in the UBE3A gene." (PMID 38248358, 2023). "Since the UBE3A gene is involved in two main important diseases associated with autism-like symptoms, there has been widespread research going on in understanding the link between this gene and autism." (PMID 38248358, 2023). "Prevention of autism-associated phenotypes, such as reduced marble burying and nest building, required embryonic Ube3a reactivation, defining a therapeutic critical period." (PMID 33616084, 2021). "With hyperfunction or overdosage of UBE3A protein, many synaptic proteins were disrupted, thus causing autism in humans." (PMID 33995501, 2021). "Based on the genetic model of common disease rare variants (CDRV), our study investigated the role of UBE3A gene variants in the pathogenesis of autism in Chinese Han population." (PMID 33308194, 2020). "Firstly, 192 patients meeting the diagnostic criteria of DSM-IV about autism and 192 healthy controls were included, UBE3A gene was selected as the candidate gene to conduct mutation screening on its coding region and adjacent non-coding regions." (PMID 33308194, 2020). "A strong correlation between AS-associated deficits and the loss of UBE3A ligase activity has been reported, as well as between an autism UBE3A-linked mutation and the hyper-activation of UBE3A." (PMID 31798818, 2019). "The autism-associated gene ubiquitin-protein ligase E3A (UBE3A) has been reported to influence WNT, BMP, and RA signaling pathways, suggesting crosstalk between various signaling pathways during autistic brain development." (PMID 31202261, 2019). "This review primarily focuses on the regulation of synaptic function and plasticity by UBE3A and how its abnormal function is associated with autism." (PMID 30568575, 2018). "On the other hand, increased UBE3A activity (via gene duplication or gain-of-function mutation) is implicated in several forms of autism, implying that UBE3A must be expressed at precise levels to allow proper neuronal function." (PMID 30364390, 2018). "Autism has been recognized as a component feature of AS, and copy number increases in the 15q11-13 chromosomal region including UBE3A are also associated with syndromic autism." (PMID 29719672, 2018).
autism (continued). "This review focuses on the critical role of UBE3A in regulating the synaptic function and how its altered activity is associated with autism." (PMID 30568575, 2018). "This indicates that UBE3A regulates Wnt signaling and that an autism-linked mutation enhanced its signaling effects, which is corroborated by other studies that place UBE3A within the Wnt signaling pathway." (PMID 30686997, 2018). "Loss-of-function mutations in the maternal copy of the imprinted UBE3A gene cause AS, while maternal duplications in the same region (15q11-13) are linked to autism." (PMID 28503211, 2017). "Increasing evidence demonstrates that overexpression or hyperactivation of UBE3A is associated with autism." (PMID 27232889, 2016). "While loss of UBE3A causes AS, a maternal 15q11–13 duplication encompassing UBE3A results in autism." (PMID 27232889, 2016). "A point mutation of UBE3A identified in an autism proband disrupts its phosphorylation by protein kinase A and increases its ligase activity." (PMID 27232889, 2016). "Coincidently, several genome-wide studies from individuals with autism identify UBE3A as an autism-risk gene." (PMID 27909399, 2016). "Evidence has been mounting that copy number variants of the gene segment including Ube3a increases autism susceptibility." (PMID 25894543, 2015). "Changes in UBE3A gene and protein expression levels in neurons are responsible for the primary underlying molecular defects in AS and 15 q duplication autism in both humans and mouse models." (PMID 23626758, 2013). "An ASD-like associated neuropsychiatric condition known as Angleman's syndrome is characterized with similar behavioral presentation (cognitive, behavioral, and motor dysfunction) as some autisms and significantly is linked to alterations of the UBE3A gene." (PMID 22937247, 2011). "In addition to increases in UBE3A copy number, a de novo autism-linked missense variant that leads to elevated UBE3A activity has also been identified." (PMID 40496139, 2025). "Moreover, precise dosing of functional UBE3A is critical for phenotypic rescue, as overexpression has been associated with autism-like phenotypes." (PMID 40950402, 2025). "We found that Ube3a can critically contribute to sex bias via transcriptional influence on genes located on the X chromosome and downstream targets of the androgen receptor, including multiple high-confidence autism-associated genes." (PMID 38996019, 2024). "Dysfunction of UBE3A is linked to autism, Angelman syndrome, and cancer." (PMID 31202261, 2019). "Interestingly, duplication, triplication or gain-of-function mutations in UBE3A gene are also linked with autism suggesting that the expression and activity of UBE3A must be precisely regulated during brain development." (PMID 30814928, 2019). "Interestingly, duplication, triplication, or gain-of-function mutations in the UBE3A gene are also linked with autism clinically distinguished by social impairments and stereotyped behaviors." (PMID 30568575, 2018). "Since HDAC2 negatively regulates synaptic plasticity and memory formation, its altered activity could lead to synaptic dysfunction in UBE3A-linked AS and autism." (PMID 30568575, 2018). "Furthermore, a de novo autism-linked UBE3A mutant (UBE3AT485A) prevents UBE3A catalytic inhibition by disrupting protein kinase A (PKA) phosphorylation inhibition toward itself and other substrates." (PMID 30686997, 2018). "However, recent work has identified EEG signatures of Dup15q syndrome, a syndromic form of autism caused by duplication of the 15q11-13 genetic region which includes UBE3A." (PMID 28503211, 2017). "Negative regulation of BMP signaling by UBE3A suggests a previously unknown molecular mechanism that underlies the pathogenesis of UBE3A-associated AS and autism." (PMID 27232889, 2016). "In addition, a recent study demonstrates that a PKA phosphorylation-defective mutation on UBE3A found in an individual with autism resulted in an increase of dendritic spine density." (PMID 27909399, 2016).
autism (continued). "Similar affects of under- and over-expression of UBE3A on membrane potential and synaptic transmission may underlie the synaptic plasticity defects observed in both AS and autism." (PMID 25948754, 2015). "Subsequent studies using a mouse that has multiple genomic copies of the Ube3a gene, thus forcing increased expression of the maternally imprinted Ube3a gene artificially, showed that indeed elevated Ube3a expression in the mouse brain is associated with autism like behaviors." (PMID 22916201, 2012). "UBE3A transcript and protein levels were increased twofold on average in dup15q samples compared to controls in our study, consistent with the hypothesis that there is increased maternal allele-specific expression of UBE3A in dup15q autism brain." (PMID 22152151, 2011). "The remaining 25% are caused by mutations in the UBE3A gene which encodes the enzyme ubiquitin protein ligase E3A, which regulates excitatory neural synapse development, a mechanism likely contributing to the cognitive dysfunction associated with AS and possibly other syndromic autisms as well." (PMID 38671997, 2024). "Thus, over and above providing a sex-specific influence on key autism-associated genes, Ube3a overdosage may be changing these emergent processes/pathways and cell types in males versus females to confer heightened male-risk and female protection." (PMID 38996019, 2024). "Therefore, appropriate gene dosage of Ube3a is critical for normal neural development–the equivalent of one active allele allows normal development, whereas too little leads to AS, and too much leads to autism." (PMID 35401134, 2022). "In addition, the UBE3A gene has been shown to be associated with autism and schizophrenia." (PMID 36012404, 2022). "Interestingly, duplication of the UBE3A gene has been associated with autism." (PMID 29693004, 2018). "Additionally, studies using neuronal cultures or transgenic mice have shown that spine density and/or shape were altered after genetic manipulation of proteins implicated in syndromic or non-syndromic autism, including neurexins/neuroligins, Shank2/3, Epac2, Tsc1/2, Ube3A and PTEN." (PMID 28258509, 2017). "Previously, UBE3A overexpression from the duplicated maternal allele had been hypothesized to be the sole explanation for autism comorbidity in dup15q syndrome as well as the increase in autism spectrum disorder (ASD) phenotypes in PWS maternal UPD compared to deletion cases." (PMID 22152151, 2011). "Nuclear increases in UBE3A in neurons impair sociability by repressing Cbln1 gene expression, a key node in an autism-related gene network due to protein–protein interactions." (PMID 40076922, 2025). "Mouse models with one or two extra copies of the UBE3A transgene, mimicking Dup15q syndrome, have shown key autism-like behaviors and decreased glutamatergic signaling." (PMID 40076922, 2025). "Mice overexpressing Ube3a display autism-related behavioral traits and impaired neuronal homeostatic synaptic plasticity driven by Ube3a-mediated retinoic acid repression." (PMID 39336109, 2024). "Proteasome health is strongly implicated in dendritic spine outgrowth, making for a connection between UBE3A and abnormal neurocytes as seen in autism cases." (PMID 39457068, 2024). "Our investigations revealed a sex-dependent effect of Ube3a overdosage on multiple translational (endo)phenotypes of relevance to autism, including changes in rsfMRI connectivity." (PMID 38996019, 2024). "We show that mice with extra copies of Ube3a exhibit sex-biasing effects on brain connectomics and autism-relevant behaviors." (PMID 38996019, 2024).